DAPK1 (death associated protein kinase 1)
Description:
Calcium/calmodulin-dependent serine/threonine kinase involved in multiple cellular signaling pathways that trigger cell survival, apoptosis, and autophagy. Regulates both type I apoptotic and type II autophagic cell deaths signal, depending on the cellular setting. The former is caspase-dependent, while the latter is caspase-independent and is characterized by the accumulation of autophagic vesicles. Phosphorylates PIN1 resulting in inhibition of its catalytic activity, nuclear localization, and cellular function. Phosphorylates TPM1, enhancing stress fiber formation in endothelial cells. Phosphorylates PRKD1 and regulates JNK signaling by binding and activating PRKD1 under oxidative stress. Phosphorylates BECN1, reducing its interaction with BCL2 and BCL2L1 and promoting the induction of autophagy. Phosphorylates TSC2, disrupting the TSC1-TSC2 complex and stimulating mTORC1 activity in a growth factor-dependent pathway. Phosphorylates RPS6, MYL9 and DAPK3. Acts as a signaling amplifier of NMDA receptors at extrasynaptic sites for mediating brain damage in stroke. Cerebral ischemia recruits DAPK1 into the NMDA receptor complex and it phosphorylates GRINB at Ser-1303 inducing injurious Ca(2+) influx through NMDA receptor channels, resulting in an irreversible neuronal death. Required together with DAPK3 for phosphorylation of RPL13A upon interferon-gamma activation which is causing RPL13A involvement in transcript-selective translation inhibition. Isoform 2 cannot induce apoptosis but can induce membrane blebbing.
Synonyms: DAPK; ROCO3
Tractability: Small molecule: a structure with a bound ligand is known; a high-quality ligand is known; it has a high-quality binding pocket; it belongs to a druggable protein family. Antibody: its Gene Ontology location is reachable by antibodies, with high confidence. PROTAC: it is named in the literature on targeted protein degradation; UniProt records ubiquitination sites on it; ubiquitination databases record sites on it; its protein half-life has been measured; a small molecule that binds it is known.
Target class: CAMK protein kinase group; Kinase; CAMK protein kinase DAPK family; Protein Kinase; Enzyme
Safety:
Unwanted effects reported when the protein is acted on. In parentheses: how it was acted on, where the effect was seen, and who reports it.
leukopenia (source: ClinPGx)
Gene: Protein-coding gene on chromosome 9 (87,497,228 to 87,709,073, forward strand). Ensembl gene ENSG00000196730.
Subcellular location: Cytoplasm (Isoform 1); Cytoplasm, cytoskeleton; Cytoplasm (Isoform 2)
Subcellular location (Human Protein Atlas): Centrosome
Pathways (Reactome):
Programmed Cell Death: Caspase activation via Dependence Receptors in the absence of ligand
Gene Ontology:
Molecular function: ATP binding; calcium/calmodulin-dependent protein kinase activity; calmodulin binding; identical protein binding; protein binding; protein kinase activity; syntaxin-1 binding; protein serine/threonine kinase activity; protein serine kinase activity
Biological process: apoptotic process; apoptotic signaling pathway; cellular response to hydroperoxide; cellular response to type II interferon; defense response to tumor cell; intracellular signal transduction; negative regulation of kinase activity; negative regulation of translation; positive regulation of apoptotic process; positive regulation of autophagic cell death; positive regulation of autophagy; protein autophosphorylation; protein phosphorylation; regulation of response to tumor cell; regulation of apoptotic process; regulation of autophagy; regulation of NMDA receptor activity; negative regulation of apoptotic process; signal transduction
Cellular component: actin cytoskeleton; cytoplasm; DAPK1-calmodulin complex; plasma membrane; nucleus; cytoskeleton; glutamatergic synapse; organelle; postsynaptic density
Genetic constraint (gnomAD): Loss-of-function variants: 27 observed, 97.2 expected, observed/expected ratio (o/e) 0.28, 90% interval 0.2 to 0.38. The upper end of that interval is the gene's LOEUF score, 0.38, which puts it in group 1 of 6, group 1 being the genes least tolerant of losing a copy. Missense variants: 1,017 observed, 1,431 expected, observed/expected ratio (o/e) 0.71, 90% interval 0.67 to 0.75. Synonymous variants: 509 observed, 573.27 expected, observed/expected ratio (o/e) 0.89, 90% interval 0.82 to 0.95.
Homologues: Orthologues: chimpanzee DAPK1 (99% identical), macaque DAPK1 (99% identical), pig DAPK1 (97% identical), dog DAPK1 (96% identical), guinea pig DAPK1 (95% identical), mouse Dapk1 (95% identical), rat Dapk1 (95% identical), rabbit DAPK1 (94% identical), tropical clawed frog dapk1 (86% identical), zebrafish dapk1 (75% identical). Paralogues in human: DAPK3 (20% identical), DAPK2 (16% identical), MYLK (12% identical), NEXN (5% identical).
Diseases named in the same sentence as DAPK1 in open-access papers:
DAPK1 is named in the same sentence as 228 diseases in open-access papers, as found by Europe PMC text mining. Sharing a sentence is not in itself a finding about the gene and the disease. The quoted sentences say what the papers report.
lung carcinoma (46 papers, 2002 to 2026). "The loss of DAPK1 expression is associated with poor prognosis and advanced tumor stages in lung cancer patients." (PMID 33201837, 2020). "Loss of DAPK1 expression via epigenetic or transcriptional regulation was associated with highly metastatic clones of lung cancer cells, whereas the restoring of DAPK1 suppressed metastatic activity." (PMID 32707646, 2020). "In murine models of cigarette smoke-induced lung cancer, hypermethylation of the TSGs, death-associated protein kinase 1 (DAPK1) and the retinoic acid receptor beta (RARB), is seen at the earliest histological stage of adenocarcinoma development." (PMID 21487403, 2011). "Seven tumor suppressor genes (CDKN2A, CDH13, MGMT, MIR137, DAPK1, RARB, and RASSF1A) consistently exhibited hypermethylation in both lung cancer and in association with smoking exposure." (PMID 42073597, 2026). "While the analysis of the cervical HeLa cell line and the lung cancer cell line A459 provided evidence for highly frequent DAPK1 expression, breast cancer cell lines showed very low levels of the DAPK1 protein." (PMID 40563561, 2025). "Other DEPs including aldo-keto reductase family 1 member B1 (AKR1B1), cyclin-dependent kinase 2 (CDK2), death associate protein kinase-1 (DAPK1), peroxiredoxin-1 (PRDX1) and aldehyde dehydrogenase mitochondrial (ALDH2) are associated with lung cancer." (PMID 40088196, 2025). "On the basis of lung cancer patient samples, hypermethylation of DAPK1 was detected in 39% of cancerous tissues; additionally, high levels of hypermethylation of DAPK1 were also found in 33% of NSCLC tissues." (PMID 37901797, 2023). "The corresponding experiment using A459 lung cancer cells showed enzymatic activity of DAPK1 towards the exogenous substrate MLC for 60 min upon release from the Noc treatment." (PMID 35154442, 2022). "Collectively, these independent experiments using different agents for the induction of cell cycle arrest provided evidence that the autophosphorylation signal of DAPK1 at pSer308 has maximal levels during mitosis of cervical and lung cancer cells." (PMID 35154442, 2022). "While in most cell types DAPK1 signals were below or at the limit of detection, only the cervical HeLa cell line and the lung cancer cell line A459 showed strong DAPK1 expression." (PMID 35154442, 2022). "Our recent study involving a murine model of inflammation-induced lung cancer analogously revealed early epigenetic changes within tumor suppressor genes Rassf1, Cdh13, and Dapk1." (PMID 33396408, 2020). "Down-regulation of DAPK1 expression has been correlated with the severity of malignancy and lymph node metastasis in various cancers including lung cancer, urinary tract carcinoma, and esophageal squamous cell carcinoma." (PMID 28934284, 2017). "Recently, several studies have investigated the roles of DAPK1 methylation in cervical cancer, lung cancer and GC." (PMID 28934284, 2017). "The data were consistent with a significant impairment of mitochondrial integrity in response to DAPK2 depletion and, in the case of A549 lung cancer cells, activation of DAPK1." (PMID 25741596, 2015). "Finally, it was shown that treatment with decitabine (5‐aza‐2′‐deoxycytidine, DAC) inhibits the DNA methylation of the DAPK1 promoter and restores DAPK1 expression in lung cancer cell lines." (PMID 27378792, 2016). "The increased expression of DAPK1 could suppress the metastasis of lung cancer cells." (PMID 35321516, 2022). "The proteins such as AKR1B1, CDK2, DAPK1, PRDX1 and ALDH2 show potential as biomarkers or therapeutic targets for radon-related lung cancer after further validation." (PMID 40088196, 2025). "We highlighted specific proteins, including AKR1B1, CDK2, DAPK1, PRDX1 and ALHD2 with potential as biomarkers for radon-related lung cancer." (PMID 40088196, 2025). "The use of a DNA methylation inhibitor called 5′-azadeoxycytidine (5-aza-dC) did not result in the restoration of DAPK-1 expression in certain B cell and lung cancer cell lines." (PMID 39081443, 2024).
lung carcinoma (continued). "DAPK1 expression silencing due to promoter methylation has been frequently found in lung cancer, in which cells with lack of DAPK1 expression appear to be more invasive and more metastatic." (PMID 28382019, 2017). "Also, DNA methylation levels of tumor suppressor genes, including death-associated protein kinase 1 (DAPK1) and retinoic acid receptor beta (RARB), are higher in lung cancer tissues than noncancerous lung tissues." (PMID 35356464, 2022). "While CDKN2A, DAPK1 and APC are found hypermethylated both in smoking and non-smoking lung cancer patients others, like APC, FHIT, RASSF1A or CCND2 are strictly correlated with smoking." (PMID 23086271, 2013). "It has to be noted that methylation status and expression of the DAPK-1 gene are not always correlated; for example, a DNA methylation inhibitor, 5′-azadeoxycytidine (5-aza-dC), did not restore DAPK-1 expression for some B cell and lung cancer cell lines." (PMID 37372454, 2023).
breast carcinoma (44 papers, 2008 to 2025). "In breast cancer patients, downregulation of DAPK1 expression is associated with tumor metastasis and recurrence." (PMID 33201837, 2020). "In this light, we investigated the potential of death-associated protein kinase 1 (DAPK1) as a biomarker for breast cancer." (PMID 32566040, 2020). "Another gene suggested to be involved in breast cancer is death-associated protein kinase 1 (DAPK1) which is known in its role of inducing cell death and recognized as a tumor suppressor gene." (PMID 31528229, 2019). "Employing ELISA, we assayed for vimentin and death-associated protein kinase 1 (DAPK1) from thawed archived (stored at -80 °C) serum samples obtained from 40 clinically confirmed Ghanaian breast cancer patients and 40 apparently healthy controls." (PMID 28616237, 2017). "This work reports on two proteins, vimentin and Death Associated Protein Kinase 1 (DAPK1) as targets for predicting tumour aggression in breast cancer development and progression." (PMID 28616237, 2017). "With the observed increased expression of DAPK1 in association with breast cancer, the protein can well be a target for therapeutics and may potentially serve as a biomarker for tumour aggression and prognosis of the disease." (PMID 32566040, 2020). "This may explain why high DAPK1 expression strongly associates with the aggressive breast cancer phenotypes like the ER-negative breast cancers, especially the triple-negative breast cancers (TNBC), which are the most aggressive, faster-growing, and highly metastatic." (PMID 32566040, 2020). "This may explain why high DAPK1 expression strongly associates with aggressive breast cancer phenotypes like the ER-negative breast cancers, especially the triple-negative breast cancers (TNBC) which are the most aggressive, fast-growing, and highly metastatic." (PMID 32566040, 2020). "For instance, in breast cancer, DAPK1 expression is often downregulated, and its methylation status is altered, indicating its role in tumorigenesis." (PMID 40918124, 2025). "One study focusing on breast cancer showed that DAPK1 inhibited the function of Pin1 isomerase by phosphorylating Ser71 in the catalytic activity site." (PMID 39057063, 2024). "DAPK1 inhibits the ability of Pin1 to induce phagosome amplification and cell transformation in breast cancer." (PMID 39057063, 2024). "Wild-type DAPK-1 has been shown to function as an apoptosis inducer in a variety of cancers including liver cancer, cervical cancer and breast cancer." (PMID 37372454, 2023). "In Tpm1.1-transfected MDA-MB-231 cells (human breast cancer cell line) which normally lack endogenous Tpm1, DAPK1 overlapped with Tpm1.1 predominantly at the cell edge, where rigidity sensing activity typically occurs." (PMID 35927990, 2022). "Clinical research data indicated that the up-regulated expression levels of DAPK1 in breast cancer patients were negatively correlated with the decreased expression of miR-127-5p." (PMID 34422899, 2021). "This is in accordance with the association study.Combination of the DAPK1 and CAVIN3 gene promotermethylations showed better results in the diagnosis of breast cancer." (PMID 34455714, 2021). "Previous studies demonstrate that DAPK1 decreases tumor cell proliferation and metastasis by promoting apoptosis in several cancers, including colorectal cancer, breast cancer, gastric cancer." (PMID 33201837, 2020).
breast carcinoma (continued). "Accordingly, breast cancer patients in this present study recorded elevated DAPK1 expression compared to controls." (PMID 32566040, 2020). "This study focused on the usefulness of DAPK1 as a prognostic blood biomarker for breast cancer and its reliability in the light of chemotherapy." (PMID 32566040, 2020). "From the immunohistochemistry results, tissue sections from breast cancer patients tended to have elevated DAPK1 expression." (PMID 32566040, 2020). "A further analysis was made by comparing the DAPK1 expression pattern between breast cancer patients already on treatment (treatment) and those yet to be placed on treatment (pretreatment)." (PMID 32566040, 2020). "For the reliability of DAPK1 as a noninvasive biomarker, the effect of chemotherapy on serum DAPK1 expression was evaluated in breast cancer patients." (PMID 32566040, 2020). "DAPK1 expression in sera of breast cancer patients was significantly higher than in the controls with the values 4.95 (SD = 1.53) ng/ml and 3.49 (SD = 1.72) ng/ml, respectively, and p value of 0.039." (PMID 32566040, 2020). "The serum concentrations of vimentin and DAPK1 were assessed in the serum samples of the breast cancer patients with respect to tumour grading." (PMID 28616237, 2017). "DAPK1 expression has been found to be elevated in certain types of breast cancers which are typically more aggressive and have poor prognosis." (PMID 28616237, 2017). "DAPK1 expression was furthermore verified on mRNA as well as on protein level in ΔpBK-ITIH5 breast cancer cells." (PMID 28231808, 2017). "The mean serum concentration of the breast cancer patients and the controls were 1800 pg/ml and 897 pg/ml respectively for vimentin and 1105 pg/ml and 372 pg/ml respectively, for DAPK1." (PMID 28616237, 2017). "In this study the serum levels of vimentin and DAPK1 were determined in archived sera of breast cancer patients and apparently healthy controls." (PMID 28616237, 2017). "Whereas vimentin concentration averaged 1462.63 ± 175.23 ng/ml in breast cancer patients and 851.29 ± 109.04 ng/ml in controls, DAPK1 concentration averaged 1105.75 ± 396.56 ng/ml and 371.09 ± 119.82 ng/ml in breast cancer patients and controls, respectively." (PMID 28616237, 2017). "Altogether, these data suggested that DNA methylation is involved in the downregulation of NTN1 and DAPK1 in human breast cancers." (PMID 27378792, 2016). "With the exception of CCND2 and DAPK1, the genes were not only frequently methylated in the tumors but also in the corresponding tumor-adjacent and tumor-distant tissues of the breast cancer patients." (PMID 26370119, 2015). "In human mammary cancer cell lines, the repression of DAPK1 mediated by MBD2 seems to actively participate in maintenance of their aggressive phenotypes when xenografted into immuno-deficient mice." (PMID 26007656, 2015). "Breast cancer cell apoptosis can be suppressed by flTF via PI3K/Akt signaling pathway and reducing IL-8 and death-associated protein kinase 1 (DAPK1)." (PMID 25084809, 2014). "The apoptosis pathway, regulated by death-associated protein kinase 1 (DAPK1) and its mediator TMS1, is also crucial; hypermethylation results in the silencing of TMS1, which promotes the proliferation of breast cancer cells, thereby contributing to disease progression." (PMID 39996888, 2025). "In that study, DAPK1 was shown to inhibit the centrosome amplification and cell transformation of cancer cells, and a negative correlation was demonstrated with Pin1, which is an oncogene in breast cancer." (PMID 39057063, 2024).